XIRP2 (xin actin binding repeat containing 2)
Description:
Protects actin filaments from depolymerization. Required for correct morphology of cell membranes and maturation of intercalated disks of cardiomyocytes via facilitating localization of XIRP1 and CDH2 to the termini of aligned mature cardiomyocytes (By similarity). Thereby required for correct postnatal heart development and growth regulation that is crucial for overall heart morphology and diastolic function (By similarity). Required for normal electrical conduction in the heart including formation of the infranodal ventricular conduction system and normal action potential configuration, as a result of its interaction with the cardiac ion channel components Scn5a/Nav1.5 and Kcna5/Kv1.5 (By similarity). Required for regular actin filament spacing of the paracrystalline array in both inner and outer hair cells of the cochlea, thereby required for maintenance of stereocilia morphology (By similarity).
Synonyms: CMYA3
Tractability: Antibody: the Human Protein Atlas places it where antibodies can reach. PROTAC: ubiquitination databases record sites on it.
Gene: Protein-coding gene on chromosome 2 (166,888,480 to 167,259,753, forward strand). Ensembl gene ENSG00000163092.
Subcellular location: Cell junction
Subcellular location (Human Protein Atlas): Plasma membrane; Nucleoplasm
Pathways (Reactome):
Sensory Perception: Sensory processing of sound by inner hair cells of the cochlea; Sensory processing of sound by outer hair cells of the cochlea
Gene Ontology:
Molecular function: actin filament binding; protein binding; actin binding; alpha-actinin binding
Biological process: actin filament organization; regulation of actin filament organization; actin cytoskeleton organization; positive regulation of protein localization
Cellular component: anchoring junction; focal adhesion; stress fiber; cell junction; cell-cell junction; Z disc
Genetic constraint (gnomAD): Loss-of-function variants: 234 observed, 288.17 expected, observed/expected ratio (o/e) 0.81, 90% interval 0.73 to 0.9. The upper end of that interval is the gene's LOEUF score, 0.9, which puts it in group 3 of 6, group 1 being the genes least tolerant of losing a copy. Missense variants: 4,640 observed, 4,373.7 expected, observed/expected ratio (o/e) 1.06, 90% interval 1.03 to 1.09. Synonymous variants: 1,490 observed, 1,497.2 expected, observed/expected ratio (o/e) 1, 90% interval 0.95 to 1.04.
Homologues: Orthologues: chimpanzee XIRP2 (99% identical), macaque XIRP2 (94% identical), rabbit XIRP2 (79% identical), pig XIRP2 (75% identical), guinea pig XIRP2 (71% identical), dog XIRP2 (70% identical), rat Xirp2 (67% identical), mouse Xirp2 (67% identical), tropical clawed frog xirp2 (39% identical). Paralogues in human: XIRP1 (12% identical).
Diseases named in the same sentence as XIRP2 in open-access papers:
XIRP2 is named in the same sentence as 38 diseases in open-access papers, as found by Europe PMC text mining. Sharing a sentence is not in itself a finding about the gene and the disease. The quoted sentences say what the papers report.
heart failure (5 papers, 2018 to 2024). Inability of the heart to pump blood at an adequate rate to meet tissue metabolic requirements. "XIRP2 is an important effector of angiotensin II signaling in cardiac muscle that binds to F-actin, and is associated with heart failure." (PMID 36322234, 2022). "The expression levels of certain genes in the heart failure stage varied considerably (e.g., Nppa, Myh7, and Xirp2)." (PMID 30375404, 2018).
breast carcinoma (4 papers, 2022 to 2024). "The high frequency of the XIRP2 mutation has been observed in various diseases, such as high-risk neuroblastoma and breast cancer." (PMID 39194571, 2024). "This is consistent with previous reports that mutant MUC4 was correlated with higher TMB and potentially associated with prognosis in pancancer, while XIRP2 mutation was potentially associated with metastasis in breast cancer." (PMID 35402515, 2022).
cardiomyopathy (4 papers, 2016 to 2019). A disease of the heart muscle or myocardium proper. "Xirp2 (also called CMYA3) is a cardiomyopathy-associated gene induced by Angiotensin-ii (Ang-ii), and a direct transcriptional target of MEF-2A." (PMID 31105874, 2019). "The associated SNPs are in the intron of XIRP2, a cardiomyopathy associated protein that is expressed in skeletal muscle and heart left ventricle, suggesting that this gene could play a role in determining left ventricular mass." (PMID 30675526, 2019). "Dysregulation of Xirp2 is linked to both cardiomyopathy and arrhythmogenesis." (PMID 30410445, 2018). "Xirp2 has been shown to be upregulated in some cardiomyopathies and mice engineered to express reduced levels of Xirp2 are partly protected from angiotensin-II-induced cardiomyopathic remodeling." (PMID 30410445, 2018).
dilated cardiomyopathy (3 papers, 2018 to 2024). Cardiomyopathy which is characterized by dilation and contractile dysfunction of the left and right ventricles. "Additionally, Xirp2 has been implicated as a genetic modifier in a childhood case of severe dilated cardiomyopathy." (PMID 30410445, 2018). "Xirp2 has been identified through single cell sequencing to be upregulated in sub-clusters of cardiomyocytes from human hypertrophic cardiomyopathy cardiac samples and mutations within Xirp2 are linked to dilated cardiomyopathy highlighting a further potential cardioprotective mechanism of 29P." (PMID 38933087, 2024).
gastric cancer (3 papers, 2016 to 2020). A primary or metastatic malignant neoplasm involving the stomach. "Other identified antigens have been correlated to other types of cancer, namely ABCA13 in ovarian cancer, XIRP2 in gastric cancer, and APOC2 expression in Non-Small Cell Lung Cancer." (PMID 32245227, 2020).
hepatocellular carcinoma (3 papers, 2023 to 2025). A malignant tumor that arises from hepatocytes. "In hepatocellular carcinoma, XIRP2 mutations are closely linked to a poor prognosis and reduced chemosensitivity." (PMID 40686517, 2025).
hypertrophic cardiomyopathy (3 papers, 2024 to 2025). A condition in which the myocardium is hypertrophied without an obvious cause. "We observed significant upregulation of heart disease markers Myh7, Xirp2, and Acta1, as well as alterations in proteins associated with hypertrophic cardiomyopathy and cardiac muscle contraction, indicating the successful establishment of the MI and TAC models." (PMID 39502510, 2024).
cardiac hypertrophy (2 papers, 2018 to 2021). "Underexpression of Xirp2 leads to cardiac hypertrophy in mice, yet mitigates the cardiac fibrosis and apoptosis induced by angiotensin II, suggesting that tight control of Xirp2 protein levels is required for a healthy myocardium." (PMID 30410445, 2018).
Arrhythmia (1 paper, 2015). Any cardiac rhythm other than the normal sinus rhythm. "Moreover, calcium handling and contractile function genes (SLN, ACTC1, PLCD4, PLCZ), potential arrhythmia-related genes (MYO5B, KCNA5), and cytoskeleton and cellular organization-related genes (XIRP2, COL8A1, KCNA6) were among the most deregulated genes in rTOF ventricles." (PMID 26252659, 2015).
deafness (1 paper, 2015). An inherited or acquired condition characterized by the complete loss of the ability to hear from one or both ears. "In addition, the ‘deafness gene and locus’ annotations indicate that human XIRP2 falls within two different but overlapping mapped deafness loci DFNB27 and DFNA16." (PMID 26209310, 2015).
hearing loss (1 paper, 2023). "The build-up of unrepaired gaps in the absence of XIRP2 may lead to the worsening phenotype, suggesting that gap repair could be necessary for the prevention of age-related hearing loss." (PMID 37294664, 2023).
Hernia (1 paper, 2023). "Yet the presence of a group of mutated genes linked to myopathies (ITGA7, NRAP, POLM, SCN5A, XIRP2) and muscular dystrophy (ITGA7) raises a question about the involvement of these muscular pathologies in hernia genesis and unsuccessful hernia repairs associated with the current case." (PMID 38021525, 2023).
myositis (1 paper, 2024). "Interestingly, XIRP2 and PSME2 were upregulated by tenfold and eightfold similarly to Ku + Myositis." (PMID 39012547, 2024).
cancer (11 papers, 2014 to 2025). A tumor composed of atypical neoplastic, often pleomorphic cells that invade other tissues. "In contrast, XIRP2, a cytoskeletal regulator linked to metastasis in other cancers, exhibited higher mutation rates in the high-risk group (p < 0.05)." (PMID 40781483, 2025). "So, BBN-related higher levels of mitochondrial Xirp2 seem to reflect cancer-induced cardiac remodeling." (PMID 30602657, 2018). "The genes preferentially mutated in metastases were MYLK, PEAK1, SLC2A4RG, EVC2, XIRP2, PALB2, and ESR1 (five of which are not significantly mutated in any type of human primary cancer)." (PMID 34771579, 2021). "PCDHGC5, PCDHAC2, SPTA1, XIRP2 and FLG seemed unrelated with cancer based the reference study." (PMID 27835590, 2016).
tumor (7 papers, 2015 to 2024). "We expected that the four genes (SACS, LRP2, WDR87, and XIRP2) that were detected in all POLE category tumours with POLE p.P286R or p.V411L would exhibit high PS if this score reflected an accumulation of biased mutation patterns." (PMID 29880869, 2018). "The gene XIRP2 that was most affected in our analysis, was reported to be expressed mainly in striated muscles, but it has not yet been connected to tumor development." (PMID 25537509, 2015).
heart disease (3 papers, 2015 to 2024). "We observed significant upregulation of heart disease markers such as Myh7, Xirp2, and Acta1, indicating the successful establishment of the MI and TAC models." (PMID 39502510, 2024).
XIRP2 also shares sentences with these, for which no sentence is quoted: Desminopathy (2 papers); lung adenocarcinoma (2); myopathies (2); Anxiety (1); bladder cancer (1); congenital myopathy (1); depression (1); esophageal cancer (1); filaminopathy (1); heroin addiction (1); idiopathic dilated cardiomyopathy (1); lung carcinoma (1); muscular dystrophy (1); myofibrillar myopathy (1); myotilinopathy (1); neuroblastoma (1); non-small cell lung carcinoma (1); ovarian carcinoma (1); peripheral neuropathy (1); polyneuropathy (1); preeclampsia (1); skin melanoma (1).